ERVH-3 (endogenous retrovirus group H member 3)
Synonyms: HERV-H/F; RP11-301G19.1; TCONS_l2_00025412
Gene: Long non-coding RNA gene on chromosome 6 (67,878,316 to 67,889,339, reverse strand). Ensembl gene ENSG00000227706.
Diseases named in the same sentence as ERVH-3 in open-access papers:
ERVH-3 is named in the same sentence as 1 disease in open-access papers, as found by Europe PMC text mining. Sharing a sentence is not in itself a finding about the gene and the disease. The quoted sentences say what the papers report.
acute myeloid leukemia (1 paper, 2013). Acute myeloid leukemia (AML) is a group of neoplasms arising from precursor cells committed to the myeloid cell-line differentiation. "A recent study in acute myeloid leukemia showed that decitabine treatment of acute myeloid leukemia cells causes hypomethylation and up-regulation of ERVH-3 expression." (PMID 24063430, 2013).